MYC (MYC proto-oncogene, bHLH transcription factor)
Diseases named in the same sentence as MYC in open-access papers (continued):
Sharing a sentence is not in itself a finding about the gene and the disease.
osteoporosis (8 papers, 2019 to 2024). A condition of reduced bone mass, with decreased cortical thickness and a decrease in the number and size of the trabeculae of cancellous bone (but normal chemical composition), resulting in increased fracture incidence. "OCs-specific MYC-deficient mice show increased bone mass caused by faulty OCs development, and the bone loss induced by osteoporosis is reduced in MYC-deficient mice." (PMID 36313705, 2022). "In a mouse model of osteoporosis, both the loss of MYC and the pharmacological inhibitory effect of ERRα reduced bone loss." (PMID 33880122, 2021). "Reduced IGF1 has been linked to the development of age-related diseases such as osteoporosis, but female MYC haploinsufficient mice had a decreased incidence of osteoporosis, consistent with the finding that, in bone, IGF1 levels were unaltered." (PMID 38510176, 2024). "A recent study reported that I-BET151 inhibited RANKL-induced osteoclastogenesis and bone loss in post-ovariectomy osteoporosis, inflammatory arthritis, and TNF-induced osteolysis mouse models by targetting MYC-NFAT axis." (PMID 30455393, 2019). "IL-18 demonstrated a protective effect against osteoporosis in our study, possibly because IL-18 promotes osteogenic differentiation of hBMSCs through the SLC7A5/c-MYC pathway." (PMID 39091505, 2024).
psoriasis (8 papers, 2015 to 2025). An autoimmune condition characterized by red, well-delineated plaques with silvery scales that are usually on the extensor surfaces and scalp. "For example, Vorinostat—an HDAC inhibitor targeting MYC—suppresses Th17 responses in preclinical models of psoriasis, suggesting repurposing potential for AD." (PMID 40655146, 2025). "Elevated MYC signaling is also implicated in psoriasis, and skin expressing psoriasis-associated GoF CARD14 mutants have both elevated MYC signatures and psoriatic features (e.g., epidermal hyperproliferation, parakeratosis)." (PMID 41346415, 2025). "Many other studies have reported that the protein expression levels of PPARG, MMP9, and MYC were also strongly correlated with the incidence of psoriasis." (PMID 35265149, 2022). "Psoriasis-like changes in DEGP expression were also observed in fibroblasts transduced with OKSM reprogramming factors (OCT4, KLF4, SOX2, c-MYC), demonstrating pathway-level overlap between psoriasis and induced pluripotency." (PMID 26251673, 2015). "Aberrations in E2F and G2/M checkpoints may drive excessive proliferation of keratinocytes in psoriasis and intestinal epithelial cells in CD, while activation of the MYC pathway may amplify pathological cell proliferation." (PMID 40406126, 2025).
rheumatoid arthritis (8 papers, 2018 to 2025). A chronic, systemic autoimmune disorder characterized by inflammation in the synovial membranes and articular surfaces. "We highlight six tocilizumab responsive genes (ARID5A, BCL3, PIM1, SOCS3, BATF, MYC) that are associated with IL-6 pathway and known to be perturbed by tocilizumab treatment in rheumatoid arthritis patients." (PMID 35064122, 2022). "In rheumatoid arthritis, there is evidence of increased MYC expression in the synovial tissue." (PMID 39028255, 2024). "To test if the newly discovered NRF2-MYC axis occurs in patients with rheumatoid arthritis (RA), we measured the expression of NRF2 and MYC in synovial OCPs from RA patients using publicly available data." (PMID 32967239, 2020).
type 2 diabetes (8 papers, 2012 to 2024). "Further, they were treated with the MYC-signaling inhibitor KJ-Pyr-9, chemotherapeutic agent carboplatin and type II diabetes medication metformin." (PMID 35269569, 2022). "PAX5, functioning as a classical transcription factor, can regulate the expression of many genes, such as MYC, WAPL, and several type 2 diabetes-related genes, including SFRP1 and SYT12." (PMID 38926764, 2024). "Next to the influence of MYC/NMYC inhibition, the effect of standard type 2 diabetes medication metformin and chemotherapeutic agent carboplatin was assessed in ECSC populations." (PMID 35269569, 2022). "Metformin, a commonly used type II diabetes drug that also activates AMPK, induced similar MYC-dependent apoptosis when combined with ABT-737." (PMID 30728358, 2019).
anaplastic thyroid cancer (7 papers, 2016 to 2025). "Network analysis revealed that MYC is one of the essential proteins that regulate NIS expression in anaplastic thyroid cancer." (PMID 35723359, 2022).
B-cell acute lymphoblastic leukemia (7 papers, 2016 to 2026). A neoplasm of lymphoblasts committed to the B-cell lineage, typically composed of small to medium-sized blast cells. "EBF1 functions as a transcription factor, which, in conjunction with PAX5, significantly regulates the developmental process of normal and malignant B-cell acute lymphoblastic leukemia by binding to MYC gene regulatory elements." (PMID 39794701, 2025). "A recent study in precursor B-cell acute lymphoblastic leukemia revealed that pre-BCR signaling regulates PI3K/AKT, FOXO1 and MYC and can be a target of SYK inhibition." (PMID 28212447, 2017).
cardiomyopathy (7 papers, 2017 to 2025). A disease of the heart muscle or myocardium proper. "The proto-oncogene MYC encodes c-Myc, which is a potential therapeutic target for cardiomyopathies." (PMID 39436707, 2024). "We found that five factor srRNA (5F-srRNA), including OCT4, KLF4, SOX2, GLIS1 and c-MYC (OKSi-GM), significantly increased iPSC generation in six different adult human fibroblasts, including old adult fibroblasts and a cardiomyopathy patient donor." (PMID 28750082, 2017). "We found that a single transfection of a five factor (5F) srRNA, containing OCT4, KLF4, SOX2, GLIS1 and c-MYC, robustly generated iPSCs from adult human fibroblasts aged 54 to 77 and from a 24 year old cardiomyopathy patient donor." (PMID 28750082, 2017). "the results showed that EPAS1 and MYC had high expression in N, and we hypothesized that EPAS1 and MYC had a possible correlation with the improvement of cardiomyopathy." (PMID 38799173, 2024). "Biallelic deficiency of the MYC target gene—complement component 1 Q subcomponent-binding protein, mitochondrial (C1QBP)—causes mitochondrial respiratory-chain deficiencies and severe cardiomyopathy." (PMID 39457090, 2024). "We then proceeded to compare the expression of stemness genes in different groups of cardiomyopathies using the same method, and screened for the same high expression of CD34, EPAS1, and MYC." (PMID 38799173, 2024). "Because EPAS1 was densely and highly expressed in C3 AGT + Fibroblasts, and MYC was densely but poorly expressed in C3 AGT + Fibroblasts, whether inhibition or promotion of EPAS1 and MYC is beneficial to the treatment of cardiomyopathy requires further study." (PMID 38799173, 2024). "Additionally, stemness genes EPAS1 and MYC, along with the regulator FOS, may play roles in modulating the biological processes of cardiac fibroblasts in cardiomyopathy." (PMID 38799173, 2024).
colorectal adenoma (7 papers, 2017 to 2025). An adenoma that arises from the colon or rectum. "These strong mtDNA signals occurred even toward the surface of the adenomatous epithelium — including in MYC protein expression — in a manner reminiscent of topographical infidelity of proliferation markers and other proteins in colorectal adenomas." (PMID 37971875, 2023).
ependymoma (7 papers, 2021 to 2025). A WHO grade II, slow growing tumor of children and young adults, usually located intraventricularly. "Notably, one posterior fossa group A ependymoma sample correlated more closely with mesenchymal GBM than with MYC-subtype ATRT, a finding suggestive of complex epigenetic relationships." (PMID 41282203, 2025). "Visualization of MYC expression for our described patient case relative to ependymoma (n = 41), glioma (n = 300), medulloblastoma (n = 129), and neuroblastoma (n = 199) patients from the UCSC Treehouse Initiative and our internal cohort confirmed this overexpression." (PMID 34895332, 2021). "We found that ependymoma tissues and lines express BET proteins and their targets MYC and MYCN." (PMID 33668642, 2021).
hepatitis B (7 papers, 2017 to 2025).
intestinal cancer (7 papers, 2011 to 2025). "Loss of CDH17 resulted in a marked down-regulation of the intestinal cancer stem cell (CSC) marker LGR5, leading to the inhibition of Wnt/β-catenin signaling, suppression of pluripotency genes such as MYC, and a subsequent reduction in stemness properties." (PMID 40595509, 2025). "Finding a significantly higher rate of MYC amplification in intestinal as compared to diffuse cancers suggests a role of MYC for progression of intestinal cancers." (PMID 25649416, 2015).
invasive ductal carcinoma (7 papers, 2009 to 2019). "Expressing both PIK3CAH1047R and deregulated MYC led to the development of invasive ductal carcinoma." (PMID 31350286, 2019). "In pancreatic neuroendocrine tumors (PanNET) the role of MYC proteins is largely unknown, although c-MYC has been suggested to act as an oncogene in a fraction of acinar cell carcinomas and ductal adenocarcinomas." (PMID 27769070, 2016).
latent infection (7 papers, 2008 to 2025). "We provide an overview of the pathways that are involved in establishing latent infection, including those regulated by MYC and NF-κB." (PMID 35328502, 2022).
malaria (7 papers, 2017 to 2023). Malaria is a serious and sometimes fatal disease caused by a parasite that commonly infects a certain type of mosquito which feeds on humans. "Antigenic stimulation from malaria is widely accepted as an insult that leads to B cell proliferation in the germinal center and increases the chance of translocation of c-MYC into the vicinity of immunoglobulin enhancer elements and progression to eBL." (PMID 32718346, 2020).
MALT lymphoma (7 papers, 2008 to 2025). An indolent, extranodal type of non-Hodgkin lymphoma composed of small B-lymphocytes (centrocyte-like cells). "One study suggests that c-MYC overexpression predicts large cell transformation and is an independent, poor prognostic marker in extranodal marginal zone lymphoma of mucosa-associated lymphoid tissue (MALT lymphoma) at levels with ≥20% positive cells." (PMID 28379189, 2017).
metabolic syndrome (7 papers, 2014 to 2023). A cluster of metabolic risk factors for CARDIOVASCULAR DISEASES and TYPE 2 DIABETES MELLITUS. "The results indicated that quercetin had an excellent binding activity with many targets, including CCND1, HIF1A, MYC, AKT1, and EGFR; therefore, it might be a key compound for the effect against dyslipidemia." (PMID 35722157, 2022).
oligodendroglioma (7 papers, 2011 to 2024). A well-differentiated (WHO grade II), diffusely infiltrating neuroglial tumor, typically located in the cerebral hemispheres. "Using fluorescent in situ hybridization (FISH) and whole genome sequencing approaches, we analysed at nucleotide resolution the organization of co-amplified sequences from the EGFR and MYC loci at successive passages of a xenografted human oligodendroglioma." (PMID 25378339, 2014). "Using fluorescent in situ hybridization and whole genome sequencing, we studied a xenografted human oligodendroglioma where the co-amplification of the EGFR and MYC loci was present in the form of dmins at early passages and of an hsr at later passages." (PMID 25378339, 2014). "In the xenografted human oligodendroglioma ODA14, the EGFR (7p11) and the MYC (8q24) loci were co-amplified and the amplified sequences resided on dmins at passage 2 (ODA14p2) and on an hsr at passage 4 (ODA14p4)." (PMID 25378339, 2014).
pancreatic neuroendocrine tumor (7 papers, 2016 to 2022). Pancreatic endocrine tumor, also known as pancreatic neuroendocrine tumor (PNET), describes a group of endocrine tumors originating in the pancreas that are usually indolent and benign, but may have the potential to be malignant. "In a study of MYC-induced pancreatic neuroendocrine tumors, MYC activation was associated with mast cell recruitment that was required for tumor growth, and treatment with cromolyn sodium prevented mast cell degranulation and decreased tumor growth." (PMID 34063789, 2021).
papillary renal cell carcinoma (7 papers, 1995 to 2024). A rare subtype of renal cell carcinoma, arising from the renal tubular epithelium and showing a papillary growth pattern, which typically manifests with hematuria, flank pain, palpable abdominal mass or nonspecific symptoms, such as fatigue, weight loss or fever. "Low RASSF10 and high MYC or high VEGF was significantly associated with poor prognosis of renal papillary cell cancer patients and the combination of two markers had a higher impact on impaired probability of survival compared with the low RASSF10 alone." (PMID 32047266, 2020). "MYC is an oncogenic downstream target of KRAS and IL6-JAK-STAT signaling and therefore we correlated the expression of MYC and RASSF10 in primary renal papillary cell carcinoma and clear cell carcinoma." (PMID 32047266, 2020). "Furthermore, we correlated overall survival of renal papillary cell carcinoma patients with RASSF10 and MYC or VEGF expression by Kaplan–Meier analysis." (PMID 32047266, 2020). "Notably, intra-tumoral foamy macrophages and psammoma bodies (features that are commonly seen in human papillary renal cell carcinoma) were lacking in the MYC tumours." (PMID 28593993, 2017).
polycystic kidney disease (7 papers, 2020 to 2024). A usually autosomal dominant and less frequently autosomal recessive genetic disorder characterized by the presence of numerous cysts in the kidneys leading to end-stage renal failure. "A role for MYC in the pathogenesis of PKD was suggested by work using the spontaneous congenital polycystic kidney Cys1cpk/cpk (cpk) mutant mouse that phenocopies human ARPKD." (PMID 38510176, 2024). "In this model, MYC overexpression was detected in polycystic kidneys, with only a minimal increase in proliferation, and also in collecting duct epithelial cells." (PMID 38510176, 2024). "Deregulated MYC expression results in a variety of oncogenic processes as well as polycystic kidney disease." (PMID 38093359, 2023). "The TAZ/Wnt-β-catenin/c-MYC axis regulates the Hippo signaling pathway of polycystic kidney disease." (PMID 36483738, 2022). "Caspase-1 knockout in female but not male RC mice restrains MYC and YAP pathways, which are central mediators of kidney pathogenesis in polycystic kidney disease." (PMID 36523654, 2022).
Richter syndrome (7 papers, 2016 to 2022). Transformation of chronic lymphocytic leukemia into aggressive non-Hodgkin's lymphoma, usually diffuse large B-cell lymphoma (immunoblastic or centroblastic variant). "Furthermore, MYC activation underlies CLL transformation in Richter’s syndrome, supporting its involvement in the switch of cancerous lymphocytes towards a more aggressive phenotype." (PMID 36226068, 2022). "Gain of function mutations of MYC has been shown in 70% of Richter syndrome cases." (PMID 34372899, 2021). "With regard to DLBCL-type Richter syndrome, the MYC pathway is deregulated in about 70% of cases, and somatic structural MYC alterations are present in 30% of cases." (PMID 35096627, 2021). "MYC is often involved in transformed indolent mature B neoplasms, such as the transformations of follicular lymphoma (FL) to DLBCL and CLL to Richter syndrome." (PMID 35096627, 2021).
thymoma (7 papers, 2015 to 2024). A neoplasm arising from the epithelial cells of the thymus. "Considering that such a focal MYC amplification was unprecedented in type A and AB thymomas clinically benign, the MYC amplification may contribute to high malignancy of thymic adenocarcinoma." (PMID 28506304, 2017). "In thymoma and thymic carcinoma, MALAT1 regulates cell proliferation by acting as an miR-145-5p sponge and contributing to c-MYC induction, following its change in subnuclear localization due to METTL3 methylation." (PMID 35529877, 2022). "Real-time PCR analysis confirmed that CCL25 was upregulated; and MYC, GADD45B, TNFRSF12 downregulated in thymoma with MG." (PMID 30787364, 2019).
cystic kidney (6 papers, 2016 to 2023). "Previous studies have demonstrated an association between MYC expression and renal cyst development in both human ADPKD and mouse PKD models." (PMID 38125876, 2023). "In contrast, we show that MYC abundance is unaltered in non-cystic kidneys from Pkhd1-deficient mice." (PMID 38125876, 2023). "In ADPKD, signaling pathways activated in renal cysts by loss of PKD1 include many known to be activated and growth-promoting in cancer including WNT/CTNNB1, PI3K/AKT, mTOR/S6K, RAF/MEK/ERK, SRC, MYC, AURKA, and others." (PMID 37542051, 2023). "Additionally, cpk mice treated with Myc-antisense oligo exhibited reduced MYC protein expression, fewer renal cysts and improved renal function." (PMID 38125876, 2023). "In the current study, we provide the first evidence that MYC is overexpressed in kidneys from ARPKD patients and confirm that MYC is upregulated in cystic kidneys from cpk mutant mice." (PMID 38125876, 2023). "MYC is a transcriptional target of the oncoprotein and transcription coactivator YAP, and the YAP-MYC signaling axis has been found to be a mediator of cystic kidney pathogenesis in a human-orthologous PKD mouse model." (PMID 36523654, 2022). "Cystic kidney disease developed in transgenic mice overexpressing MYC, whereas mice that spontaneously lost the transgene did not develop renal cysts." (PMID 38125876, 2023). "In contrast, renal MYC expression levels were not altered in several Pkhd1 mutant mice that lack a significant cystic kidney phenotype." (PMID 38125876, 2023). "In contrast, MYC protein levels were not elevated in kidneys from four different Pkhd1 mutant mouse model lines (Pkhd1cyli, Pkhd1del3-4, Pkhd1del3-67, or Pkhd1del67) that did not exhibit a cystic kidney phenotype." (PMID 38125876, 2023). "Furthermore, the lack of enhanced MYC expression in Pkhd1 mutant mice without cystic kidney phenotype suggests differences in the function of mouse and human FPC-CTDs." (PMID 38125876, 2023).
dysplasia (6 papers, 2004 to 2024). A usually neoplastic transformation of the cell, associated with altered architectural tissue patterns. "Of the 21 dysplasia samples, CDKN2A loss was found in four samples, MYC amplification in two, and EGFR in one." (PMID 35897137, 2022). "Confirming these data, TNF-α expression has been shown to increase along the metaplasia-dysplasia-carcinoma sequence, leading to an increase in the proto-oncogene MYC via a β-catenin mediated pathway." (PMID 28042960, 2017). "Progressive overexpression of MYC in the oesophageal metaplasia-dysplasia-adenocarcinoma sequence has been observed previously; prior to this study however, the expression of other members of the MYC/MAX/MAD network had not been studied in any detail in the oesophagus." (PMID 18493233, 2008).